B2M (beta-2-microglobulin)
Diseases named in the same sentence as B2M in open-access papers (continued):
Sharing a sentence is not in itself a finding about the gene and the disease.
lymphoma (continued). "We also identified frequent genetic alterations in immune surveillance genes (B2M and CD58), suggesting immune escape contributes to lymphoma relapse." (PMID 25123191, 2014). "However, significantly higher levels of cfDNA were found in lymphoma patients with elevated levels of lactate dehydrogenase (LDH), elevated levels of beta 2-microglobulin (B2-MG), and advanced stage or B-symptoms." (PMID 38254810, 2024). "As expected, the combination of pevonedistat and anti-PD-1 had no therapeutic efficacy in A20 B2M-KO lymphomas." (PMID 37031300, 2023). "Differently higher serum proteins in canine lymphoma were observed in beta-actin cytoplasmic 1 (ACTB, p=0.04), Hp (p=0.002), beta-2 microglobulin (β2M, p=0.007), beta-2 glycoprotein 1 (APOH, p=0.03), metalloproteinase inhibitor 1 (TIMP-1, p=0.03), and CD44 antigen (p=0.02)." (PMID 35765478, 2022). "Six candidate increased proteins in canine lymphomas were beta-actin cytoplasmic 1 (ACTB, p=0.04), haptoglobin (p=0.002), beta-2 microglobulin (aaaaaaaa2M, p=0.007), beta-2 glycoprotein 1 (APOH, p=0.03), metalloproteinase inhibitor 1 (TIMP-1, p=0.03), and CD44 antigen (p=0.02)." (PMID 35765478, 2022). "Thrombocytopenia (18.3% vs. 0% vs. 23.9%; p-value = 0.01), elevated B2M (58.6% vs. 24.1% vs. 52.2%.; p-value = 0.00), and serum EBV detection rate (40.5% vs. 31.0% vs. 11.9%; p-value = 0.00) were more common in AITL compared to other TFH lymphomas or PTCL-NOS." (PMID 33990228, 2021). "CRISPR-Cas9-mediated TCRα/β and B2M knockout to generate “off-the-shelf” allogeneic CAR T cells is also evaluated in other clinical trials for CD19+ leukemia and lymphoma patients (NCT04035434), multiple myeloma patients (NCT04244656) and renal cell carcinoma patients (NCT04438083)." (PMID 32903482, 2020). "CRISPR-Cas9-mediated knockout of TCRα/β and B2M in combination with lentiviral delivery of an anti-CD19 CAR into allogeneic T cells resulted in universal CAR T cells (UCART019) that are clinically tested in relapsed or refractory CD19+ leukemia and lymphoma patients (NCT03166878)." (PMID 32903482, 2020).
lung cancer (22 papers, 2018 to 2025). A malignant neoplasm involving the lung. "Inactivation of the MHC-I complex has been reported in many human cancers, and B2m mutations have been found in various tumor types, including lung cancers." (PMID 38195889, 2024). "For the disruption of antigen presentation, acquired homozygous loss of beta-2-microglobulin (B2M) was identified in an acquired ICI-resistant lung cancer sample, which decreased the expression of HLA class I and disrupted the antigen-presentation." (PMID 35884355, 2022). "Impaired human leukocyte antigen (HLA) class I antigen processing and presentation due to homologous loss or down-regulation of B2M has also been found as a mechanism of acquired resistance to ICIs in lung cancer patients." (PMID 30409126, 2018). "CRISPR-mediated knock-out of B2m in an immunocompetent lung cancer mouse model conferred resistance to PD-1 blockade in vivo, demonstrating the causal relationship between loss of B2m and resistance to ICIs." (PMID 30409126, 2018). "Likewise, a study on lung cancer confirms that the loss of B2M is correlated with disrupted HLA-1 antigen processing and presentation, which leads to acquired resistance to PD-1 blockade." (PMID 30294272, 2018). "Importantly, high frequency of initial B2M mutations were found in patient-derived xenografts for lung cancer, suggesting patients with this gene mutation may experience primary resistance to CPIs." (PMID 30294272, 2018). "As an example, the Jcomp score across the 11 lung cancer tissues was positively correlated with the expression of genes coding MHC-class I protein (B2M, HLA-A, HLA-B, and HLA-C), which are among the biomarkers for immunotherapy response." (PMID 40170080, 2025). "B2M defect induces resistance in ICIs-treated lung cancer patients, while upregulation of B2M enhances the efficacy of immunotherapy." (PMID 40191187, 2025). "B2-microglobulin (β2M) is essential in stabilizing cell surface expression of HLA class I. Studies suggested that genomic alterations in B2M were related to both primary and acquired resistance to ICIs in some solid tumors, including melanoma and lung cancer." (PMID 36959853, 2023). "Immunocompetent lung cancer mouse, whose B2M genes were knocked out, also showed the resistance to ICIs." (PMID 35069896, 2022). "In lung cancer, genetic inactivation of B2M prevents the positioning of HLA class I protein on the cell surface, resulting in a deficiency in HLA class I complex." (PMID 36611830, 2022). "B2M inactivation was recently reported to be a recurrent event in lung cancer and potentially affects response to anti-PD-1/anti-PD-L1 therapies." (PMID 30327465, 2018). "Class I HLA disruption mediated by B2M deletion leads to ICIs escape in lung cancer." (PMID 35069896, 2022). "In addition, B2M protein is also a growth‐promoting molecule for human prostate, breast, and lung cancers, as well as renal cell carcinoma." (PMID 33960680, 2021). "For example, loss of function mutations in and genomic loss of B2M, an essential component of MHC class I antigen presentation machinery, have been linked with resistance across several tumors, including colorectal cancer, melanoma and lung cancer." (PMID 31416487, 2019). "Similarly, downregulation of B2M was found in lung cancer patient-derived xenografts from immune checkpoint inhibitor-resistant tumors." (PMID 31416487, 2019). "In several studies of acquired resistance to immune checkpoints inhibitors in lung cancer, and MMR-d cancers were described homozygous deletion of B2M and alterations of B2M respectively." (PMID 37038154, 2023). "The expression of HLA-I antigens was evaluated in 68 lung cancer tissue samples by Immunohistochemical staining using antibodies against monomorphic determinants of HLA-ABC complex, locus-specific antibodies and anti-β2-microglobulin (B2M) antibodies." (PMID 29423109, 2018).
prostate carcinoma (19 papers, 2012 to 2025). A carcinoma that arises from epithelial cells of the prostate gland. "Additionally, B2M has functionally been implicated in prostate cancer as its over-expression in cancer cells induced rapid tumour growth in bone, while disrupting B2M signaling by specific small interfering RNA produced a regression of previously established prostate tumours." (PMID 22355332, 2012). "Employing B2M-targeting antibody promoted prostate cancer cell death through the activation of the caspase-9-dependent pathway." (PMID 38743119, 2024). "In prostate cancer, B2M instigated the cAMP-dependent PKA signaling pathway, thereby facilitating the proliferation and survival of cancer cells within the bone microenvironment." (PMID 38743119, 2024). "In prostate cancer, studies found that advanced prostate cancer is connected with an increase in serum levels of B2M." (PMID 37510802, 2023). "In line with this, our ex vivo gene expression analysis suggests a role for APM and B2M epigenetic regulation in prostate cancer patients, which merits further study." (PMID 36050516, 2022). "In an immunocompetent spontaneous prostate cancer mouse model, B2M antibody was able to prevent tumor growth." (PMID 33960680, 2021). "In human prostate cancer cells, it has been reported that blockade of downstream signaling of B2M induces tumor cell apoptosis." (PMID 33960680, 2021). "Transfection of 293F fibroblasts as well as prostate cancer cells LNCaP, C4–2B, and PC3 produced cells with stem-like colony morphology and down-regulated B2M, indicating that the proteins encoded by these genes were functional." (PMID 31146720, 2019). "Contrastingly, it has been reported that B2M expression is significantly altered in hypoxic prostate cancer cells out of a panel of 16 reference genes for qRT-PCR." (PMID 27835695, 2016). "Evidence of the real-time detection will be presented for Prostate Specific Antigen (PSA) and β-2-microglobulin (B2M) secreted by prostate cancer cells following induction by dihydrotestosterone (DHT)." (PMID 26784243, 2016). "From a biological point of view, SPR results demonstrated that PSA, the most used biomarker of prostate cancer, and B2M were secreted in similar amounts." (PMID 26784243, 2016). "Given BAY1082439 treatment can significantly increase the expression of B2M in PTEN-null prostate cancer cells, this result indicates that BAY-I treatment may induce proliferation and activation of tumor antigen-specific T cells." (PMID 35013322, 2022). "In contrast B2M expression was found to be significantly altered in hypoxic prostate cancer cells." (PMID 34035373, 2021). "B2M secreted protein level might then be high enough to be considered as a new biomarker of prostate cancer." (PMID 26784243, 2016). "There have been a number of reports implicating B2M as a candidate prostate cancer biomarker." (PMID 22355332, 2012). "Thus, B2M may potentially serve as a biomarker for prostate cancer progression and a novel drug target for the treatment of bone metastasis which requires further study." (PMID 22355332, 2012). "B2M is a component of the MHC I complex and has been shown to be released by LNCaP prostate cancer cells in culture in response to androgen stimulation." (PMID 22355332, 2012). "Liquid biopsy of exosomes isolated from patients with prostate cancer revealed that exosomes are enriched for genes that are hallmarks of prostate cancer, such as androgen receptor, kallikreins (KLK2), cyclin-dependent kinase inhibitor 1A (CDKN1A), KLK10, JUN, and B2M (β2 microglobulin)." (PMID 36726968, 2022). "It has been reported that targeting B2M with a specific anti‐B2M antibody represents a potential novel therapeutic approach for the treatment of human renal cell carcinoma, prostate cancer, and hematological malignancies." (PMID 33960680, 2021).
metastatic melanoma (18 papers, 2017 to 2025). A melanoma that has spread from its primary site to another anatomic site. "B2M frameshift mutation was discerned in a patient with intractable stage IV metastatic melanoma after receiving the combination therapy of ipilimumab and nivolumab." (PMID 40191187, 2025). "We report a case of a patient with immunotherapy refractory intracranial metastatic melanoma after initial response to ICI who had acquired B2M mutation." (PMID 33447351, 2020). "Similarly, we previously reported a patient with refractory intracranial metastatic melanoma who acquired beta-2-microglobulin (B2M) mutation, which contributes to PD-1 resistance." (PMID 39065766, 2024). "In one case report, investigators tracked the chronological sequence of appearance of B2M gene mutation in several successive metastatic melanoma lesions and a lymph node biopsy-derived cell line obtained after immunotherapy with a dendritic cell vaccine (DCV) transfected with autologous tumor mRNA." (PMID 36046045, 2022). "first proved that in patients with metastatic melanomas who were treated with immunotherapy, B2M was lost, suggesting that the loss of B2M might be a possible factor that facilitates cancer cell acquisition of immunotherapy resistance." (PMID 36119033, 2022). "More research is essential to delineate whether TVEC or TMZ has efficacy in immunotherapy refractory metastatic melanoma with acquired B2M mutation." (PMID 33447351, 2020). "In metastatic melanoma patients, LOH and mutations in B2M were associated with primary immune resistance and the loss of response to ICI therapy." (PMID 36611830, 2022). "A study on metastatic melanoma patients treated with ICI therapies found decreased B2M and/or HLA class I expression in some patients harboring B2M gene alterations and showing primary or acquired ICI resistance." (PMID 35531074, 2022). "Identification of a series of potentially indicative biomarkers for immunotherapy in metastatic melanoma, including B2M." (PMID 33854972, 2021). "An association could be found in a cohort study between elevated B2M expression and superior immune responses and significantly prolonged survival in metastatic melanoma patients undergoing ICIs treatment." (PMID 40191187, 2025). "We evaluated whether the differential expression of B2M and its correlated genes (CD1D, CD1B, and FCGRT) is associated with poor responses to anti-PD1 in metastatic melanoma." (PMID 37077920, 2023). "A study of 17 metastatic melanoma patients found that Beta-2 microglobulin (B2M), another essential component of the HLA class I antigen presentation machinery, was mutated, deleted or subject to LOH in 29% of patients whose tumours did not respond to immune checkpoint blocking therapy." (PMID 36476325, 2022). "Then, we normalized and combined four transcriptomic publicly available cohorts of metastatic melanoma patients receiving anti-PD1 therapies and evaluated the survival responses regarding B2M differential expression." (PMID 37077920, 2023). "Mutations in Janus kinase 1/2 (JAK1/2) and beta-2-microglobulin (B2M) were found in both primary and acquired resistance to anti-PD-1 antibody (pembrolizumab) or anti-CTLA-4 (ipilimumab) in metastatic melanoma patients." (PMID 34827646, 2021). "Analysis of longitudinal tumor biopsy specimens from metastatic melanoma patients treated with anti-CTLA-4 or anti-PD-1 identified a subset of initial responders whose disease progressed with resistant tumors no longer expressing B2M." (PMID 31703593, 2019).
renal failure (18 papers, 2007 to 2024). "In these disease states, high levels of B2M are associated with poor prognosis, development of kidney failure and secondary amyloidosis." (PMID 33284430, 2021). "By Cameron, B2M, which is another significant toxin in blood purification, accumulates slowly in the body under CRF conditions, and therefore, a great deal of time is required for renal failure associated with a high B2M concentration." (PMID 20569462, 2010). "Beta-2-microglobulin (B2MG_HUMAN), and cystatin c (CYTC_HUMAN) showed elevated urinary levels in patients with acute renal failure." (PMID 37873871, 2023). "Lack of CD56 expression has been associated with a number of adverse clinicopathologic factors including higher B2M levels and higher incidence of renal insufficiency and therefore thought to represent more aggressive disease." (PMID 37250623, 2023). "In recent years, there has been an increasing number of studies on the role of beta-2-microglobulin (β2M) in the development of acute kidney injury (AKI) and CKD." (PMID 34830560, 2021). "We found that the capacities of cystatin C and B2M to detect acute kidney injury were better than that of serum Cr." (PMID 17519026, 2007). "As previously shown in other groups of patients, in our experience serum cystatin C and B2M are better markers than serum Cr to detect acute kidney injury in critically ill children." (PMID 17519026, 2007). "Serum cystatin C and B2M were confirmed as easy and useful markers, better than serum creatinine, to detect acute kidney injury in critically ill children." (PMID 17519026, 2007). "In our experience, serum cystatin C and B2M were confirmed as simple and useful markers, better than serum Cr, to detect acute kidney injury in critically ill children." (PMID 17519026, 2007). "Abnormally high concentrations of β2 microglobulin (B2M) (5.6 mg/L) were found, which could also be found not only in lymphoproliferative disorders but in renal failure as well." (PMID 35664896, 2022). "Given that beta-2 microglobulin is excreted mainly via kidneys, renal failure itself might lead to increased serum beta-2 microglobulin levels." (PMID 27764777, 2016). "Independent of muscle mass, serum B2M levels begin to increase early in renal failure." (PMID 36648873, 2022). "Secondly, ISS stage III is defined by a serum level of beta-2 microglobulin >5.5 mg/dL, a finding that reflects not only high tumor load in the bones (which may need RT), but also renal insufficiency (which does not need RT)." (PMID 25741475, 2015).
viral infection (18 papers, 1995 to 2025). "Increased expression of b2m is a classic response against viral infection and a cellular response to type I IFN." (PMID 39264994, 2024). "Finally, we wished to determine if B2M was able to block virus infection by interacting directly with the virus particle." (PMID 36574441, 2022). "The upregulated genes associated strongly with microglial activation and included antigen presentation genes (Tap1, B2m) and activation genes (Ccl12, IL-34 and Icam1) that occur in neurodegenerative disease, brain injury and viral infection, and are NF-κB regulated." (PMID 35464428, 2022). "Upon viral infection or malignant transformation, ensuing alterations in gene expression result in the generation of novel sets of peptides which can form complexes with specific HLA class I heavy chains and beta 2-microglobulin." (PMID 7640226, 1995). "The regulation of MHC antigen processing and presentation during viral infection involves four genes: AP3B1, B2M, CD1A, and CD1D." (PMID 41155393, 2025). "The CXCL10/11high basal cells also had upregulated mRNA encoding for complement components (C1R and C1S), MHC class I (HLA-A, HLA-B, HLA-C, and B2M), and metalloproteases MMP2 and MMP13, the latter reducing repair during viral infection in bronchial epithelial cells." (PMID 40980495, 2025). "At the gene level, we found that NF could significantly induce a set of ISG expressions, such as MCL1, IFITM3, B2M, BST2, OAS1, and PKR to function against virus infection." (PMID 35910807, 2022). "B2 M is the small extracellular immunoglobulin‐like subunit of the major histocompatibility complex (MHC) class I molecule, and its levels are elevated in inflammation, liver or renal dysfunction, some viral infections, and malignancies." (PMID 33078901, 2020). "Additionally, immune response pathways, including antigen processing and presentation, viral myocarditis were significantly enriched, with key molecules such as HLA, B2M, and TAP1/2, suggesting that viral infections trigger immune-related processes in neuronal cells." (PMID 40166347, 2025). "However, although genes related to MHC I such as beta-2 microglobulin and TAP proteins were up-regulated, it appears that activation of this pathway may not be as important in ASRV infection as it is in other viral infections such as ISAV." (PMID 23226193, 2012).